RNU6-507P (RNA, U6 small nuclear 507, pseudogene)
Gene: Small nuclear RNA gene on chromosome 3 (149,779,009 to 149,779,108, reverse strand). Ensembl gene ENSG00000251854.
Homologues: Orthologues: chimpanzee U6 (99% identical), macaque U6 (79% identical), dog U6 (63% identical), pig U6 (57% identical), rabbit U6 (57% identical). Paralogues in human: RNU6-200P (74% identical), RNU6-672P (71% identical), RNU6-796P (71% identical), RNU6-1290P (70% identical), RNU6-132P (70% identical), RNU6-15P (70% identical), RNU6-345P (70% identical), RNU6-746P (70% identical), RNU6-1 (69% identical), RNU6-10P (69% identical), RNU6-1145P (69% identical), RNU6-116P (69% identical), and 1285 more.